TLR4 (toll like receptor 4)
Diseases named in the same sentence as TLR4 in open-access papers (continued):
Sharing a sentence is not in itself a finding about the gene and the disease.
Anxiety (67 papers, 2012 to 2026). Intense feelings of nervousness, tension, or panic often arise in response to interpersonal stresses. "Genetic studies in humans evidenced that TLR4 single nucleotide polymorphisms are associated with anxiety, suicidal behavior, and other symptoms in patients with first-episode depression." (PMID 40558558, 2025). "To note, TLR-4 activation is also associated with visceral hypersensitivity and related behavioral disorders, resulting in episodes of anxiety and recurrent flares of abdominal pain." (PMID 36009057, 2022). "TLR4 single gene polymorphisms were associated with suicide and anxiety scores in MDD patients, while methylation levels of TLR4-associated CpGs were related to the severity of depressive symptoms." (PMID 35782423, 2022). "ELS‐mediated activation of TLR4 in rodents has been implicated in reprogramming of neural anti‐inflammatory pathways and also results in increased anxiety behavior during adulthood." (PMID 34042301, 2021). "A splenic increase in Il1β and Tlr4 with cortical Vcam expression strongly associated with the anxiety-like behavior while splenic IL-10 associated with IL-1β from both the PFC and cortex, predicted depressive-like behavior." (PMID 34248950, 2021). "Knockout of TLR4 protects against ethanol withdrawal associated anxiety-like behavior and memory impairment." (PMID 28210782, 2017). "Moreover, increased TLR4 protein levels in the hippocampus were associated with behavioral despair, social avoidance, and anxiety-like behaviors, which were normalized with fluoxetine treatment, direct TLR4 blockade, or genetic deletion." (PMID 40558558, 2025). "In this work, we investigated the pain and anxiety behavioral phenotypes of wild-type and TLR4-deficient juvenile mice subjected to repeated SDS and evaluated the engagement of TLR4 by measuring dimerization in the spinal cord, dorsal root ganglia, and prefrontal cortex." (PMID 40072079, 2025). "Importantly, in vivo studies utilizing TLR4-deficient mice demonstrated a critical role of TLR4 in ethanol-induced neuroinflammation as well as cognitive dysfunction and anxiety behavior." (PMID 37626919, 2023). "Furthermore, it has been revealed that TLR2 and TLR4‐associated signaling pathways are involved in cognitive dysfunction and anxiety behavior by inducing neuroinflammation." (PMID 35898162, 2022). "Thus, TLR4/NF‐κB is a major signaling pathway involved in the pathogenic mechanisms of anxiety and represents a novel direction for our future studies." (PMID 34878231, 2022). "Dex promotes NREM sleep and stabilizes circadian rhythms via activation of SCN^VIP neurons and modulates neuroinflammation and anxiety-like behavior by targeting the TLR4-MyD88-NF-κB signaling pathway." (PMID 41222826, 2025). "In the elevated plus maze, sh-TLR4 rats exhibited a significant increase in both open arm entries and time spent in the open arms, indicating reduced anxiety-like behavior." (PMID 41222826, 2025). "Further studies have shown that TLR4 knockout (KO) mice exhibit increased anxiety-like behavior and reduced social interaction compared to wild-type control mice." (PMID 40558558, 2025). "Treatment with dex significantly reduced the expression of TLR4, MyD88, and NFκBp65 in HH-exposed rats and alleviated neuroinflammatory responses and anxiety-like behaviors." (PMID 41222826, 2025). "TLR4 expression correlates with MDD symptoms, anxiety, and weight loss, and postmortem studies on MDD suicides reveal elevated TLR4 levels in the brain and blood mononuclear cells." (PMID 38792602, 2024). "Binge drinking, often intertwined with cognitive impulsivity, anxiety, and smoking habits, triggers neuroimmune signaling through TLR4." (PMID 38792602, 2024). "TLR2 and TLR4 have been identified as crucial mediators in generating neuroinflammation, leading to neuronal changes and anxiety behavior." (PMID 35898162, 2022).
Anxiety (continued). "Different molecular signaling pathways, such as BDNF, TrkB, TLR2, and TLR4, are involved in the pathogenesis of anxiety and cognitive decline." (PMID 35898162, 2022). "Experimental animals subjected to chronic stress manifested the activation of NF‐κB mediated by upregulation of TLR4, leading to neuroinflammation, oxidative stress, anxiety, and depressive‐like behaviors." (PMID 34878231, 2022). "Thereby, TLR4 knockout mice show an increase of anxiety-like behaviour and a decrease of social interaction compared to the control mice." (PMID 36079861, 2022). "In conclusion, we report, for the first time, that TLR4 invalidation in IEC during the ABA model induced a sex-dependent response: a delayed body weight loss in males and an increase of anxiety-like behaviour in females." (PMID 36079861, 2022). "In another study, ellagic acid has also been reported to improve anxiety and sleep by inhibiting the TLR4 signaling pathway." (PMID 34595202, 2021). "EA has long been reported to have a strong neuroprotective effect, but no studies have yet reported its effects on the memory impairment and anxiety induced by SD via the Nrf2 and TLR4 pathways." (PMID 32433038, 2020). "In conclusion, the results showed that CSDS increased the TLR4 protein level in hippocampus and induced behavioral despair, social avoidance, and anxiety‐like behavior." (PMID 31945269, 2020). "Fluoxetine blocked the increased expression of TLR4 and reversed behavioral despair, social avoidance, and anxiety‐like behavior induced by CSDS." (PMID 31945269, 2020). "TLR4 inhibition during development has been found to improve hippocampus-dependent spatial, contextual, and motor learning, whereas TLR4 inhibition during adulthood alters anxiety-like behavior as assessed by the open field and elevated plus maze." (PMID 32708167, 2020). "Taken together, EA alleviated memory impairment and anxiety in sleep-deprived mice potentially by inhibiting TLR4 and activating Nrf2." (PMID 32433038, 2020). "Our findings showed that fluoxetine not only reversed behavioral despair, social avoidance, and anxiety‐like behavior, but also normalized increased expression of hippocampal TLR4 induced by CSDS." (PMID 31945269, 2020). "Fluoxetine normalized the increased expression of TLR4 and reversed behavioral despair, social avoidance, as well as anxiety‐like behavior induced by CSDS." (PMID 31945269, 2020). "For example, systematic challenge of prenatal or neonatal mice with lipopolysaccharide (LPS; a TLR4 agonist) or poly(I:C) (a TLR3 agonist) causes autism-like (e.g. impaired social interaction) and schizophrenic-like behaviors, and increases anxiety." (PMID 31684953, 2019). "This suggests that while the genotypes are best distinguished on the basis of repetitive behaviors, gavage treatment affects anxiety-like and repetitive behavior differently in male WT and Tlr4−/− mice." (PMID 29351816, 2018). "In this experiment, we observed that oral gavage of LPS significantly increased anxiety behavior in both males and females, but a specific TLR4 antagonist, (+)-naloxone, had opposing effects on anxiety and repetitive behavior in males and females." (PMID 29351816, 2018). "In experiment 1, male wild-type (WT) and Tlr4−/− mice were tested for locomotor, anxiety-like, and repetitive behaviors in an automated open field test apparatus, 2 h after oral gavage of LPS or saline." (PMID 29351816, 2018). "Conversely, activation of TLR4 by LPS administration to mice on PND 14 increased the expression of the cytokines in both plasma and the brain, and caused long-term anxiety-like behavior." (PMID 28738878, 2017). "The data presented here expand our view of the role of TLR4 in learning and memory, and anxiety behaviors." (PMID 23071817, 2012).
Anxiety (continued). "Furthermore, intracerebral infusion of a TLR4 antagonist in adult mice alters anxiety responses and impairs the developmental regulation of spatial reference memory and fear learning, but does not significantly alter hippocampus-dependent cognitive behavior." (PMID 40558558, 2025). "Moreover, mice with TLR4 were completely protected from the effects, indicating its role in anxiety, at least regarding ethanol use, and indicating the importance of the immune system as a marker for potential therapeutic use in the future." (PMID 40508224, 2025). "Moreover, high-fat diet fed mice display decreased TLR2 and increased TLR4 mRNA expression in the hippocampal tissue and anxiety- and depressive-like behaviors compared to lean-fed mice." (PMID 40558558, 2025). "Here, using social defeat stress (SDS), we investigated the chronic pain and anxiety-like behavior phenotype in juvenile male mice and the contribution of TLR4 activity in the dorsal root ganglia, spinal cord, and prefrontal cortex in the development of persistent pain caused by social stress." (PMID 40072079, 2025). "Inhibition of the TLR4-MyD88-NFκB pathway significantly alleviated both hormonal disturbances and anxiety-like behaviors in HH rats.Dex treatment, especially at high doses, suppressed inflammatory responses, normalized hormone levels, restored sleep gene expression, and improved behavioral outcomes." (PMID 41222826, 2025). "Pathogenesis involved in IBS, such as intestinal barrier damage, intestinal dysbiosis, abnormal intestinal peristalsis, increased visceral sensitization, and anxiety behaviors, are related to the interactions among TLR4, the NF-κB pathway, the pro-inflammatory effects, and the CRFs." (PMID 39749341, 2024). "Additionally, ellagic acid can improve anxiety, possibly by inhibiting toll-like receptor 4 and activating NF-E2-related factor, to reduce anxiety." (PMID 39494343, 2024). "Our previous research results show that administration of BER to inhaled METH-addicted rats via modulation of neuroinflammation (NF-Κb, TLR4, Sirt1, and α-actin) improves anxiety-related behavior and decreases relapse (in the conditional place preference task)." (PMID 36594063, 2023). "At the end of the 12-week experiment, anxiety-like behavior was evaluated by the light/dark box test; compulsive-like behavior by Marble burying, transcriptional regulation of genes Lrrk2, Tlr4, Nfat, Drd1, Drd2, Il6, Il1β, Il10, and iNOS by RT-qPCR; and inflammatory markers by flow cytometry." (PMID 37063320, 2023). "Overall, the observed overexpression of HMGB1 and TLR4 could be mediating the anxiety-like behavior observed 2 weeks after NA injection." (PMID 35803999, 2022). "For example, sesamol is a liposoluble lignan isolated from sesame products and an in vivo study found that it reduced anxiety-like behaviors of mice with inflammatory bowel disease through decreasing neuroinflammatory responses via inhibition of TLR-4/NF-κB pathway." (PMID 36358502, 2022). "It is well established that TLR4 may contribute to anxiety-like behaviour through central and/or peripheral actions." (PMID 36079861, 2022). "The importance of the immune system in generating anxiety symptoms resulting from alcohol withdrawal is demonstrated by the fact that elimination of TLR4 and/or TLR2 in mice inhibited the production of inflammatory mediators in the striatum and prevented the onset of anxiety symptoms." (PMID 35095609, 2021). "Male offspring were especially susceptible to these deleterious effects, showing greater changes in microglial TLR4 signaling that were accompanied by behavioral deficits in anxiety-like behavior, contextual and auditory cue fear conditioning and the forced swim test." (PMID 33061891, 2020). "GPS may be useful for developing an agents for the treatment of neuropsychiatric disorders, such as anxiety, due to its antiinflammatory activities and the modulation of NF-κB/iNOS/TLR4/BDNF." (PMID 30460112, 2018).
Anxiety (continued). "Therefore, GPS dose-dependently mitigated LPS-induced anxiety-like behaviors via appropriate modulation of NF-κB/TLR4/BDNF." (PMID 30460112, 2018). "If anything, there was a trend toward LPS increasing time spent in the center zone in Tlr4−/− mice, suggesting that LPS may interact with other innate immune receptors to decrease anxiety." (PMID 29351816, 2018). "Indeed, the role of TLR4-activated chemokines including MCP-1, using TLR4-KO mice, in mediating chronic ethanol-induced neuroinflammation and anxiety-related behavior has been reported." (PMID 26484872, 2015). "This suggests that TLR4 is important for regulating normal anxiety responses." (PMID 23071817, 2012). "HET may also ameliorate inflammation-induced anxiety by inhibiting TLR4 signaling." (PMID 36034871, 2022). "Under this condition, microglia are overactivated via the Toll-like receptor 4/nuclear factor-κB signalling pathway, and the levels of interleukin-1β, interleukin-6 and tumour necrosis factor-α significantly increase, inducing depressive and anxiety-like behaviours." (PMID 36209126, 2022). "The activation of TLR4 also plays an important role in the behavioral and cognitive dysfunctions associated with alcohol-induced neuroinflammation damage since these deficits, such as memory impairments and anxiety-like behaviors, are not observed in TLR4-deficient mice after alcohol treatment." (PMID 30687006, 2018). "However, no detrimental changes in anxiety and aversive memories, and spatial reference memory acquisition, have been observed in the TLR4-deficient mice." (PMID 28738878, 2017). "Finally, In contrast to TLR4 deficiency, TLR3-deficient mice exhibit impaired anxiety responses." (PMID 23071817, 2012). "It was shown that deletion of TLR2 and TLR4 eliminated repeated social defeat stress (R-SDS)-induced social avoidance and anxiety in mice." (PMID 41459223, 2025). "Highlight the significant role of the HMGB1/TLR4 pathway in chronic stress-induced VHS, anxiety-like behaviors." (PMID 39749341, 2024). "We found that CSDS increased TLR4 protein levels in the hippocampus and induced behavioral despair in FST, social avoidance in SIT, and anxiety‐like behavior in LDT." (PMID 31945269, 2020). "Collectively, the data indicate that the α2/TLR4 signal in the VTA controls binge drinking, which is one form of excessive drinking that is related to impulsivity and anxiety." (PMID 29690521, 2018). "Deletion of TLR4 in Tph2-expressing serotonergic neurons reduces anxiety-like behavior in male mice but not in female mice." (PMID 40558558, 2025). "Maternal resource deprivation interacts with gestational exposure to diesel exhaust particles (DEP) by inducing long-term offspring anxiety-like behavior and sex-specific gene expression changes; e.g., only male offspring with prenatal DEP and maternal stress showed increased Tlr4 and Casp1." (PMID 34429070, 2021). "The results indicated that the SJE could inhibit inflammatory response in the brain of DSS-induced mice by regulating the TLR4/NLRP3 signaling pathway, while suppressing apoptosis and oxidative stress, thereby improving the depressive/anxiety-like behavior." (PMID 34977127, 2021). "In our first experiment, LPS increased anxiety-like behavior in male WT mice whereas no such effect was found in male Tlr4−/− mice." (PMID 29351816, 2018). "In experiment 1, oral gavage of LPS increased anxiety-like behavior in male WT mice but not in Tlr4−/− mice." (PMID 29351816, 2018). "Oral administration of LPS significantly increased anxiety-like behavior in WT mice but not in Tlr4−/− mice." (PMID 29351816, 2018). "We noted that despite TLR4-KO mice showing comparable behavioral responses as the WT mice, prenatal and postnatal ethanol treatment induced neither anxiety nor memory dysfunctions in these mice." (PMID 28738878, 2017).
Anxiety (continued). "For instance, Guerri and colleagues found that binge ethanol-induced innate immune activation in mice impairs novel object recognition memory and increases anxiety-like behavior, an effect that is not found in TLR4 knockout mice." (PMID 28210782, 2017). "TLR4 antagonist infusion into the cerebral ventricles of adult mice did not affect cognitive behavior, but instead affected anxiety responses." (PMID 23071817, 2012). "In contrast, antagonism of TLR4 in adult TLR4+/+ mice has no impact on cognition, and instead affects anxiety responses." (PMID 23071817, 2012). "We also used lipopolysaccharide (LPS), an agonist of TLR4, in an in vitro model of macrophage IL-1β and TNF release and in an in vivo paradigm of “sickness behavior,” measuring inflammation-induced signs of anxiety, hypolocomotion, and suppressed exploration in mice." (PMID 36091684, 2022). "TLR4 and TLR2 knockout mice are protected from chronic ethanol (5 weeks) induction of striatal and serum cytokines/chemokines, autophagy impairments, glial activation, NFκB activation, cortical caspase-3 activation, anxiety-like behavior, and working memory deficits." (PMID 33806288, 2021). "As to the anxiety‐like behavior, we found that unstressed TLR4‐KO mice spent less time in light area in the LDT compared to unstressed WT mice, which was supported by a recent study in which mice lacking TLR4 had a robust anxiety‐like phenotype (Femenia, Qian, Arentsen, Forssberg, & Heijtz, 2018)." (PMID 31945269, 2020). "Taken together, these data indicated that acute injection of TLR4 inhibitor just prior to behavioral test could block behavioral despair, but not social avoidance and anxiety‐like behavior induced by CSDS." (PMID 31945269, 2020). "Consistent with the TLR4 inhibitor's effect on behavioral despair, we found that knockout of TLR4 could reverse the behavioral despair indexed by the immobility duration but not social avoidance and anxiety‐like behavior induced by CSDS." (PMID 31945269, 2020). "Our results showed that one injection of TAK‐242 prior to behavioral test could block behavioral despair but not social avoidance and anxiety‐like behavior, suggesting that TLR4 is effective to modulate despair phenotype induced by CSDS." (PMID 31945269, 2020). "Taken together, these data indicate that knockout of TLR4 could block behavioral despair, but not social avoidance and anxiety‐like behavior induced by CSDS." (PMID 31945269, 2020). "Interestingly, blockage of TLR4 signaling by infusing a TLR4 antagonist into the cerebral ventricles of adult mice does not affect cognitive behavior but induces anxiety." (PMID 31684953, 2019). "Interestingly, TLR4 inhibition in adult mice, but not developmental TLR4 deficiency, resulted in altered anxiety levels, as evident in performance in the open field arena and elevated plus maze task, suggesting that physiological TLR4 signaling may also be involved in anxiety/exploratory behaviors." (PMID 23071817, 2012). "Either acute injection of TLR4 inhibitor or knockout of TLR4 prevented the CSDS‐induced behavioral despair, but not social avoidance and anxiety‐like behavior." (PMID 31945269, 2020). "Interestingly, the knockdown of TLR4 in Tph2 neurons, which are highly expressed in the DRN, reduces anxiety-like behavior in male but not female mice, suggesting that TLR4 in Tph2 neurons regulates anxiety-like behavior in a sex-dependent manner." (PMID 41459223, 2025). "In the present work, an overexpression of some genes related to inflammation (the pattern recognition receptor TLR4 and the alarmin HMGB1) was found in the hypothalamus of NA treated rats concurrently with the anxiety-like behavior (i.e. at 2 weeks but not at 10 weeks)." (PMID 35803999, 2022). "However, directly blocking TLR4, by using either TLR4 inhibitor TAK‐242 or knockout of TLR4, only inhibited behavioral despair, but not social avoidance or anxiety‐like behavior induced by CSDS." (PMID 31945269, 2020).